CLDN18 (claudin 18)
Diseases named in the same sentence as CLDN18 in open-access papers (continued):
Sharing a sentence is not in itself a finding about the gene and the disease.
cancer (continued). "In cancer models, CLDN18 dysregulation alters cytoskeletal dynamics and activates signalling cascades involving RhoA/ROCK and β-catenin, which modulate cell adhesion, migration, and inflammatory gene expression." (PMID 41226477, 2025). "Our findings provide compelling evidence supporting the clinical development of HM2-CAR-T cells as a promising immunotherapeutic strategy for CLDN18.2-expressing cancers." (PMID 41550919, 2025). "The results show antigen-specific CD69 expression on TAC01-CLDN18.2 cells after incubation with CLDN18.2-positive cancer cells." (PMID 39404622, 2025). "This review summarizes recent advances in CLDN18.2-targeted therapies and molecular imaging for cancer management." (PMID 41019366, 2025). "We then highlight emerging therapeutic strategies targeting this biomarker, followed by an in-depth discussion of novel applications and limitations of CLDN18.2-targeted theranostics in various cancers represented by digestive system tumors." (PMID 41019366, 2025). "One direction is to develop and test ADCs that act against other established therapeutic targets in this group of cancers, such as CLDN18.2." (PMID 39809756, 2025). "Subsequently, we investigated the expression levels of CLDN18 across various cancer types and found that CLDN18 was highly expressed in multiple cancer types." (PMID 38774870, 2024). "Drug sensitivity analysis revealed that the effects of niclosamide were reduced in three cancers as CLDN18.2 expression increased." (PMID 39555091, 2024). "The results revealed large differences in the expression of most immune-related genes between the high- and low-CLDN18.2 groups of the three cancers." (PMID 39555091, 2024). "The results revealed limited associations between CLDN18.2 expression and TMB and MSI, with a positive correlation observed only in certain cancers." (PMID 39555091, 2024). "Pan-cancer analysis revealed that CLDN18 was prognostically and immunologically relevant across multiple types of cancer." (PMID 38774870, 2024). "Specifically, in individual cancers, low CLDN18.2 expression was more conducive to prognosis in BLCA, ESAC, and PAAD." (PMID 39555091, 2024). "Immune infiltration analysis revealed correlations between CLDN18 expression and various types of immune cells in several cancer types, including LIHC." (PMID 38774870, 2024). "In our own cohort, a correlation was observed between high levels of CLDN18.2 expression and advanced cancer stage, poor prognosis, and heightened infiltration of CAFs." (PMID 38200591, 2024). "A phase I clinical trial investigating AMG910 for patients with CLDN18.2 positive cancers is underway." (PMID 38554200, 2024). "These cells demonstrate upregulation of CLDN18; claudin proteins have an emerging role in regulation of cancer stem cell populations, and isoform CLDN18.2 is subject to ongoing investigation as a therapeutic target." (PMID 38630793, 2024). "Claudin-18 provides evidence for a role of claudin-18.2 in the oncogenic properties of cancer cells by regulating EGFR/ERK signaling." (PMID 36959784, 2023). "In this section, we review the factors that regulate CLDN18 expression, as well as the roles of CLDN18 in cancers of the GI tract." (PMID 36969060, 2023). "CLDN18 (M) was expressed in all gastric‐type cancers and tended to be expressed more often in intestinal‐ and usual‐type cancers than in iSMILE‐type cancers (p < 0.001)." (PMID 35861118, 2023). "The cancer-promoting effects of CLDN18 are mostly manifested in cancers with ectopic activation of this factor." (PMID 36969060, 2023). "Being selectively expressed only in short-lived differentiated gastric cells, other than in some neoplastic tissues, claudin-18.2 was recognized as a safe pan-cancer target [16 19]." (PMID 35925388, 2022). "The CLDN18 protein is the most studied among the CLDNs, since it is specifically expressed in stomach and GC tissue, compared to other tissues or cancers, which makes it a potential therapeutic target." (PMID 35053454, 2022).
cancer (continued). "In The Cancer Genome Atlas, GC was classified into four new molecular subtypes, and CLDN18–ARHGAP fusion was observed in the genomically stable type." (PMID 35053454, 2022). "Dr. Zea Borok (University of California, San Diego) presented data addressing the role of claudin-18 (Cldn18) in lung regeneration and cancer." (PMID 35762622, 2022). "We found that 28% of adenocarcinomas were immunoreactive for claudin-18, with cutoff values of ≥1% at any intensity, while 6% of cancers showed immunoexpression of ≥75% with 2+/3+ score." (PMID 35925388, 2022). "In our cohort, mostly in CrD-SBAs, CLDN18 positivity was also observed in some cancer-adjacent dysplastic lesions, and in most cases there was concordance in CLDN18 expression between the dysplastic growth and the invasive neoplasm." (PMID 35925388, 2022). "Claudin-18 is a tight junction protein expressed in various cancer types including gastric and gastroesophageal junction cancer." (PMID 34834447, 2021). "The fusion-positive cancer cells stained diffusely positive for Claudin 18 in addition to membrane staining, suggesting that localization was altered." (PMID 32668412, 2020). "Genetic alterations of CLDN18 in different cancers were examined using the TCGA PanCan Atlas studies." (PMID 32668412, 2020). "Expression of CLDN18 was restricted to lung and stomach in normal tissues, was significantly downregulated in GC, but was ectopically overexpressed in some other cancer types." (PMID 32668412, 2020). "CLDN18 immunostaining was observed in cancer cells at the apical and lateral membranes of glandular cells and occasionally on the entire circumference of infiltrating cells." (PMID 30034621, 2018). "This mutual exclusivity was confirmed in our study (data not shown) and provides strong genetic evidence that both the CLDN18-ARHGAP fusion and RHOA mutations are cancer drivers in the same pathway." (PMID 30034621, 2018). "Almost all fusion-positive cancers showed positive CLDN18 immunostaining, suggesting that CLDN18-ARHGAP fusion expression is indispensable in the cases with gene fusions." (PMID 30034621, 2018). "In agreement, in vitro studies have demonstrated that CLDN18-ARHGAP26-transfected cancer cells showed reduced cell-cell adhesion and augmented invasiveness." (PMID 30034621, 2018). "When CLDN1, CLDN4, and CLDN18 were analyzed, as single markers, across 18 cancer tissue types, the AUC values were 0.756 (p=1.4×10-4), 0.647 (p=0.156), and 0.792 (p=2.5×10-4), respectively." (PMID 29050243, 2017). "When CLDN1, CLDN4, and CLDN18 were analyzed throughout the 18 cancer types as a multi-marker set, the AUC value was 0.850 (p=3.3×10-4)." (PMID 29050243, 2017). "Representative GC cases with submucosal invasion showed that dense claudin-18 staining was evident at the invasive front of submucosal invaded-cancer cells, and Ki-67 LI was low at the lesion." (PMID 24073219, 2013). "In a case with low claudin-18 staining at the invasive front of submucosal invaded-cancer cells, Ki-67 LI was high at the lesion." (PMID 24073219, 2013). "In the race to discover new targeted therapies for CLDN18.2-positive cancer patients, these compounds may offer increased affinity and specificity for their intended targets, but additional toxicities may make commercial success more difficult to achieve." (PMID 40136475, 2025). "At around 28%, we found slightly fewer CLDN18.2 positive carcinomas." (PMID 40775258, 2025). "Moreover, we observed an increase in CLDN18 expression levels with the progression of several cancer types (e.g., LIHC, KIRC)." (PMID 38774870, 2024). "Overall, the results of the drug sensitivity analysis reveal that several drugs may specifically treat CLDN18.2-positive tumors among these three cancers." (PMID 39555091, 2024). "Moreover, the differences in methylation and CNV levels between the high- and low-CLDN18.2 expression groups were compared in each cancer type." (PMID 39555091, 2024).
cancer (continued). "Moreover, Kaplan–Meier analysis of these cancers individually revealed that high CLDN18.2 expression was a poor prognostic factor in BLCA (P = 0.013), ESCA (P = 0.021) and PAAD (P = 0.002)." (PMID 39555091, 2024). "The results revealed that CLDN18 is expressed to some extent in various cancers, which may be related to the prevalent expression of claudin family genes in epithelial cells (Günzel and Yu, 2013)." (PMID 39555091, 2024). "Because drug sensitivity analysis is important for cancer research, in upper gastrointestinal tract cancers, we predicted the sensitivity scores for 545 drugs and analyzed the correlation between the scores and CLDN18.2 expression." (PMID 39555091, 2024). "Among these cancers, CLDN18.2 appeared less common in research related to BLCA." (PMID 39555091, 2024). "Furthermore, CLDN18 was subjected to pan-cancer analysis and related in vitro regulatory experiments, establishing its central targeting role." (PMID 38774870, 2024). "Silva pattern C cancers expressed higher levels of CLDN18 (M) than Silva pattern A and B cancers (p = 0.004), whereas the CLDN18 (N) expression levels in cancers showing Silva pattern A were significantly higher than those in cancers exhibiting Silva patterns B and C (p < 0.001)." (PMID 35861118, 2023). "Cancer cells were considered CLDN18‐positive if membranous or nuclear staining was present." (PMID 35861118, 2023). "In tissues of early-stage GC removed via endoscopic mucosal resection or endoscopic submucosal resection, the Ki-67 labeling index at the invasive front inversely correlated with the CLDN18 expression level, suggesting that a decrease in CLDN18 expression promotes cancer invasion in early-stage GC." (PMID 35053454, 2022). "Recently, claudin 18.2, a transmembrane protein normally expressed in gastric mucosa, has been recognized as a novel pan-cancer therapeutic target, and several clinical trials with claudin-18-directed drugs have shown promising results on various gastrointestinal malignancies." (PMID 35925388, 2022). "The CLDN18-ARHGAP fusion protein may disrupt the structure of the wild-type CLDN18 protein, which may impact the cellular adhesion of cancer cells, increasing their migration and invasion ability." (PMID 34834447, 2021). "The results in Gene Expression Profiling Interactive Analysis 2 (GEPIA2) showed that CLDN18 was strictly expressed in gastric and pulmonary tissues but downregulated in corresponding cancer tissues, although the level was still high in GC compared with other cancers." (PMID 32668412, 2020). "In cancer cells, CLDN18 was considered as positive only if membranous staining was present." (PMID 31235864, 2019). "However, we saw haphazard tendencies of R1/2-resected carcinomas to express CLDN18.2 more frequently, which had lost significance after appliance of the multiple testing procedure as well as multivariate analysis." (PMID 31332522, 2019). "In addition, expression of claudin-18 was observed in the hyperplastic, dysplastic and cancer components of all cases." (PMID 24765156, 2014). "One possible explanation could be that fixation of anti-CLDN18 might interfere with the biological function of claudin 18 in cancer cells, probably leading to cell death." (PMID 23088623, 2012). "Monoclonal antibody therapies—bemarituzumab (FGFR2b), zolbetuximab (CLDN18.2), and ramucirumab (VEGFR2)—represent a precision oncology approach targeting key cancer mechanisms: oncogenic signaling, epithelial antigen-driven proliferation, and angiogenesis." (PMID 41227318, 2025). "Most CLDN18.2-targeted imaging studies have used transfected cell lines or PDX models due to the scarcity of naturally and stably expressing CLDN18.2 cancer cell lines." (PMID 41019366, 2025). "One emergent biomarker from several types of cancer, especially for GBC, is claudin 18 (UniprotKB—P56856)." (PMID 38534210, 2024).
cancer (continued). "The tight junction protein claudin-18 (CLDN18), is often expressed in various cancer types including gastric (GC) and gastroesophageal adenocarcinomas (GECs)." (PMID 34834447, 2021). "TFF1, IGFBP7, JUNB, CLDN18 and LINC01133 genes were among the top genes of the primary cancer cells." (PMID 34055623, 2021). "CLDN18 fusions are expected to inhibit the RHOA pathway, and in some contexts, RHOA inhibition promotes cancer cell invasion in vitro." (PMID 30034621, 2018). "The frequency of the CLDN18-ARHGAP26/6 fusions among the DGCs was consistent with the TCGA data, from which eight (14.8%) of 54 GS-type cancers had the fusions." (PMID 30034621, 2018). "Immunostaining patterns of CDH17 and CLDN18 were investigated in whole sections of cancer tissue from representative cases (9 cases for CDH17 and 5 cases for CLDN18), including primary tumors and nodal metastases to remove some of the focal biases of TMAs." (PMID 27580354, 2016). "Therefore, the loss of claudin-18 expression in advanced GC may not simply demonstrate the character of the cancer." (PMID 24073219, 2013). "The results indicated that methylation levels significantly differed between the high- and low-CLDN18.2 expression groups in all cancers, whereas CNV levels did not significantly differ between two groups in LUSC and TGCT." (PMID 39555091, 2024). "Cancer-related databases such as UALCAN, TNMplot, GEPIA, muttarget and Human Protein Atlas (HPA), and the Kaplan–Meier Plotter platform were used to analyze the relationship between CLDN18 and the clinical characteristics, as well as prognosis of HCC." (PMID 37438735, 2023). "Positive CLDN18 expression was more common in well-differentiated carcinomas, whereas focal or negative CLDN18 expression was more common in higher-grade carcinomas." (PMID 37629433, 2023). "Notably, all these CLDN18–ARHGAP fusions share a common RhoGAP domain after gene translocation and are thought to promote carcinogenesis and cancer progression by inactivating Rho." (PMID 35053454, 2022). "A previous study showed that positive membrane CLDN18 expression was significantly associated with non-antral GCs (P = 0.016), diffuse type (Lauren classification) (P = 0.009), and EBV-associated cancers (P < 0.001)." (PMID 35811317, 2022). "Survival analysis showed a non-significant trend towards a worse cancer-specific survival for claudin-18-positive cases." (PMID 35925388, 2022). "However, high CLDN18 expression is maintained in stage III, IV disease (p = 0.019) and 158/350 (45%) samples presented at least 50% of the cancer cells stained with ≥2+ intensity for CLDN18." (PMID 34834447, 2021). "According to the results of our study, claudin-18.2 positive membrane CLDN18 expression was statistically associated with non-antral GCs, Lauren diffuse type and with EBV-associated cancers." (PMID 34834447, 2021). "Positive membrane CLDN18 expression was statistically associated with non-antral GCs (p = 0.016), Lauren diffuse type (p = 0.009), and with EBV-associated cancers (p < 0.001)." (PMID 31235864, 2019). "As a limitation of this study, it is still not clear that this decreased claudin-18 level at the submucosal invasive front is actually involved in cancer metastasis, because it is difficult to follow the natural history of early GCs." (PMID 24073219, 2013). "The levels of claudin-18 were significantly lower in cancer cells than in non-IM and IM, as well as significantly lower in IM compared to non-IM." (PMID 24073219, 2013).
cancer (continued). "Claudin 18 has two isoforms: CLDN18.1, mainly expressed in the lung, and CLDN18.2, a specific isoform overexpressed in the stomach, which has emerged as an ideal biomarker because it is widely expressed only in cancer cells, particularly gastric and gallbladder cancer." (PMID 38534210, 2024). "CLDN18- and/or EPCAM-expressing epithelial clusters in the Uniform Manifold Approximation and Projection of total cells were further divided into 9 different groups with several undefined clusters, including gastric, intestinal, and dysplastic or cancer cell lineages." (PMID 37196797, 2023). "Furthermore, in CLDN18 knockout mice, gastric mucosal atrophy and convulsive polypeptide expression alteration (SPEM) occur after paracellular H+ ion leakage and parietal cell death, and SPEM was suggested as the origin of cancer stem cells." (PMID 35053454, 2022). "Indeed, while in the stomach the loss of CLDN18 protein was reported to promote inflammation and tumorigenesis, as described in knockout models, de novo expression of CLDN18 in small bowel and colon-rectum of IBD patients seemed to be part of the inflammation-metaplasia-dysplasia-cancer process." (PMID 35925388, 2022). "Finally, we showed a non-significant trend towards a worse cancer-specific survival in CLDN18-positive SBAs, as reported in CRC, even though very discordant data are reported in the Literature for other gastrointestinal cancers [25 26 28 37 42 47 48]." (PMID 35925388, 2022). "However, it has also been reported that CLDN18 knockout mice do not progress to cancer while maintaining atrophic gastritis and SPEM status." (PMID 35053454, 2022). "Moreover, claudin-18 (≥1%) was positively associated with cytokeratin 7 (CK7) and MUC5AC expression, showing CK7+/MUC5AC+ carcinomas the highest rate of positive cases, whereas a negative correlation was found between claudin-18 and CDX2 expression." (PMID 35925388, 2022). "Claudin-18 is likely involved in TJ formation in normal gastric cells, while cancer cells, which typically do not form TJ's, may have a more available form of claudin-18." (PMID 16836752, 2006). "However, the biological function of claudin-18, which might be involved in cancer cell behavior, has never been examined." (PMID 24073219, 2013). "In addition, CLDN18.2-CAR-T cells showed cytotoxicity against cancer cell lines expressing CLDN18.2, which was more than two-fold than that against cancer cell lines not expressing CLDN18.2." (PMID 38700775, 2024). "Compared to control, cells with CLDN18-ARHGAP26 overexpression got no advantage in cell proliferation, but had significantly increased ability of cell migration, which is considered as a late event in cancer progression." (PMID 29961079, 2018).